FOXM1 (forkhead box M1)
Diseases named in the same sentence as FOXM1 in open-access papers (continued):
Sharing a sentence is not in itself a finding about the gene and the disease.
tumor (continued). "NB-55, the only orally active inhibitor, was quite effective in reducing primary tumor growth and reducing the metastatic load and suppressing these EMT and FOXM1 target gene expressions in the lung metastatic lesions." (PMID 32961773, 2020). "Our data clearly show that HMGA1 and FOXM1, in addition to regulating VEGFA, have a strong impact on tumor angiogenesis." (PMID 31311575, 2019). "a–c mRNA expression of FOXM1 (a), KIF4A (b), and CENPF and KIF20A (c), in human HCC and non-tumor tissues based on data from TCGA." (PMID 31072351, 2019). "Forkhead box M1 (FOXM1) is a member of the Forkhead box transcription factor family, which plays critical roles in tumor initiation, proliferation, metastasis and drug resistance." (PMID 31497532, 2019). "FOXM1 is highly expressed in aggressive tumors including PDA regulating tumor growth proliferation, migration, and angiogenesis." (PMID 30873387, 2019). "Reduced expression of Ki-67 was observed in the tumor mass of MDA-MB-231 cells silenced for HMGA1 and FOXM1." (PMID 31311575, 2019). "Forkhead box protein M1 (FOXM1) was identified as an oncogenic transcription factor and master regulator of tumor progression and metastasis." (PMID 30782607, 2019). "Conversely, overexpression of FOXM1 (SCC-25 FOXM1 #2) in SCC-25 cells increased target gene transcripts involved in tumorigenesis (VEGFA and AURKB) and decreased those related to tumor suppression (TRAIL Receptor 1 and 2)." (PMID 30978209, 2019). "To validate the essential role of CREB3L1, E2F7, FOXM1, and NFYB in ATC progression, we detected their gene expression levels in both human tumor tissues and cell lines." (PMID 31183379, 2019). "Downregulation of FoxM1 also coincided with increased YAP phosphorylation, indicative of tumor suppression." (PMID 30744076, 2019). "Increased H3K79me2 enrichment was observed at the FOXM1 promoter in both BMDCs from TBM, and in BMDCs from wild‐type mice cultured with tumor‐conditioned medium that mimics the tumor microenvironment (TME)." (PMID 30628173, 2019). "In summary, CDCA5, FOXM1, KIF15, MCM2, and ZWINT was involved in cell mitosis and supported our research results by affecting the cell cycle regulation of tumor pathogenesis." (PMID 31708970, 2019). "circTP63 is correlated with larger tumor size and higher TNM stage in LUSC patients and promotes cell proliferation by functioning as a ceRNA to upregulate FOXM1." (PMID 31324812, 2019). "FOXM1 protein expression was significantly correlated with TNBC subtype (p < 0.001), ER/PR+ tumors (p = 0.045) and tumor grade (p = 0.013) by chi squared analysis." (PMID 30572639, 2018). "IKK1/2 inhibitor and knockdown of IKK1/2 also sensitize CRC cells to JQ1 treatment and repress c-myc and FOXM1 expression, indicating that NF-κB is the primary target for Bortezomib to synergize with JQ1 to inhibit tumor growth." (PMID 29472532, 2018). "As one possibility, Cui and co-workers demonstrated that the Forkhead box M1 (FOXM1) transcription factor regulates c-MET expression via ERK, AKT and STAT3 pathways, creating a positive feedback loop that promotes tumor growth." (PMID 30567565, 2018). "This study shows that FOXM1 and UBE2C are overexpressed and positively correlated in ESCC as well as in a wide range of distinct tumor types." (PMID 29596365, 2018).
tumor (continued). "Next, we re-analyzed FOXM1 and UBE2C expression data from over 7400 samples from 25 different tumor types deposited in the TCGA database and detected a positive correlation between the expressions of the two genes in all tumor types analyzed." (PMID 29596365, 2018). "In brief, the tumor-bearing experiments in nude mice indicate that knockdown of LOC653786 suppresses RCC xenograft growth and FOXM1 expression in vivo." (PMID 29552295, 2018). "We have shown that, across multiple tumor types, NPM binds to FOXM1, and their interaction is required for sustaining the level and localization of FOXM1." (PMID 30089730, 2018). "The results of this study show that FoxM1 is highly expressed and is strongly related to poor prognosis and adverse pathological factors in ICC such as multiple tumors, tumor diameter > 5 cm, positive lymph node metastasis, and advanced TNM stage." (PMID 30580327, 2018). "Our results show that FOXM1 and UBE2C expression present a positive correlation in normal tissues and in 25 distinct tumor types, including ESCC, where these genes are overexpressed." (PMID 29596365, 2018). "In the present study, we confirmed that FoxM1 regulated ADAM-17 expression in vivo and in vitro, leading to enhanced cell proliferation and tumor growth." (PMID 29776401, 2018). "Futhermore, immunohistochemical staining revealed decreased levels of FOXM1, AURKA and Nanog expression in Dox-induced tumours, compared with the control DMSO-treated cells." (PMID 28114286, 2017). "Since SOX2 is a marker of stem-like and dedifferentiated tumor cells, activation of SOX2 can contribute to increased invasiveness of lung tumors in FoxM1-ΔN transgenic mice." (PMID 29267283, 2017). "Taken together, our studies demonstrate that FoxM1 and Gli1 are aberrantly elevated in CRC tumor tissues." (PMID 28148279, 2017). "A number of TFs were significantly altered in two or more tumour types, including ZEB1, JUN, ELK1, FOXM1, while others were limited to a single type, such as FOXD1 in HNSC and FOXL1 in KIRC." (PMID 28139702, 2017). "To extend our findings to human CRC tissues, we investigated the relationship between FOXM1 and ABCC10 expression in tumor tissues of 20 CRC patients." (PMID 28051999, 2017). "Both FOXM1 and AGR2 induce tumor growth, progression, invasiveness and maintain mucinous characteristics in PIMAs." (PMID 29267283, 2017). "After screening the gene expression of ABC transporters and FOX molecules, we found that FOXM1 and ABCC5 were consistently overexpressed in the TR NPC cells and in patient tumor tissues." (PMID 28277541, 2017). "ABCC5 expression was low when FOXM1 expression was low in the same tumor tissue and the higher FOXM1 expression, the stronger was ABCC5 expression in the same tumor tissues." (PMID 28277541, 2017). "FOXM1 and ABCC5 were consistently expressed in these same tumor tissues, although the clinical history of patients and their sensitivity to chemotherapeutic agents were unavailable." (PMID 28277541, 2017). "One key driver of chemoresistance is the transcription factor Forkhead box protein M1 (FOXM1) that regulates cell cycle proliferation, maintenance of genomic stability, DNA damage response, and cell differentiation in numerous tumor entities." (PMID 29228593, 2017). "FOXM1 and the ABC transporter ABCC5 were consistently overexpressed in paclitaxel-resistant NPC cells and tumor tissues." (PMID 28277541, 2017). "Prx I protected tumor cells from ROS-induced cell death and positively regulated the H-rasG12V-induced ERK/FoxM1/Nrf2 pathway to promote tumorigenesis." (PMID 27517622, 2016). "When ERβ is activated by the selective agonist KB9520, SIRT1 and FOXM1 are down regulated, resulting in increased acetylated AKT1 and interaction with PARP1, HSC70 and GADPH in tumor cells, both in vitro and in vivo." (PMID 26885609, 2016).
tumor (continued). "First, the downregulation of FOXM1 by two different FOXM1 shRNAs decreased glycolysis in both A2780 and SKOV3 cells, suggesting a metabolic mechanism for tumor growth in EOC cells." (PMID 27351131, 2016). "Here we provided the first evidence that eEF2K expression is transcriptionally regulated by FOXM1 and that the FOXM1/eEF2K axis promotes cell TNBC proliferation, survival, migration/invasion and contributes to tumor growth and progression." (PMID 26918606, 2016). "We next examined the effects of FOXM1-B (FOXM1#2) and FOXM1-C (FOXM1#1) siRNAs on cell proliferation and colony formation in MDA-MB-231 and BT-20 cells by using a clonogenic assay, which measures the ability of tumor cells to grow and form foci." (PMID 26918606, 2016). "FOXM1 transcription factor is considered as one of the key transcriptional drivers of TNBC and the master regulator of tumor metastasis, promoting cell invasion and disease progression." (PMID 26918606, 2016). "Clonogenic survival analysis was done in U251 tumor cells and GBAM1 stem cells to measure the enhancement of radiosenstivity after FOXM1 inhibition." (PMID 27764801, 2016). "Emerging evidences suggest that enhanced FoxM1 levels lead to the acquisition of EMT phenotype, which contributes to tumor cell aggressiveness along with a series of molecule changes of epithelial or mesenchymal markers." (PMID 25935853, 2015). "It has been previously demonstrated that the TP63/TP53L, ERG, GRHL1/Get-, HNF1A/TCF-1, SPI1/PU.1, WT1 and GLIS2, FOXM1 and FOXP3 transcription factor networks, which are mediated by HNF4A, can regulate the expression of Trop2 in tumor tissues." (PMID 25779928, 2015). "We also found significant increases in FoxM1 and Sox2 expression in GBM cells after irradiation both in vitro and in vivo orthotopic tumor models." (PMID 26444992, 2015). "The Cancer Genome Atlas (TCGA) data indicated that the FOXM1 locus is amplified in ~12% of HGSOC, greater than any other tumor type examined, and that FOXM1 amplification correlates with increased expression and poor survival." (PMID 26243836, 2015). "Here, we demonstrate a novel function of CDC20 mediating TIC proliferation, self-renewal and tumor growth by connecting two key TIC nodes, FOXM1 and p21CIP1/WAF1." (PMID 25938542, 2015). "Our study demonstrates a novel integration of FOXM1, CDC20, and p21WAF1/CIP1 with TIC proliferation, survival and tumor growth." (PMID 25938542, 2015). "The expression levels of FoxM1, PDGF-A, and phospho-AKT were significantly higher in tumor tissues than in non-tumor tissues." (PMID 25869208, 2015). "Inverse correlation between Foxm1 and SPDEF expression levels was also found when metastatic and primary tumor samples were compared." (PMID 25254494, 2014). "Studies determined the direct role of miR-149 in the Forkhead Box M1(FOXM1) mRNA to prevent the EMT process, which is important in proliferation of tumor." (PMID 25337946, 2014). "Downstream target pathways of FOXM1 include vascular endothelial growth factor (VEGF), matrix metalloproteinase-2 (MMP-2), and β-catenin, each of which promotes tumor formation and progression." (PMID 23404835, 2013). "A univariate analysis showed that tumor stage (P<0.0001), lymph node status (P<0.0001), TNM stage (P<0.0001) and FoxM1 expression (P<0.0001), each predicted a significantly worse prognosis in NSCLC patients." (PMID 23536876, 2013). "FOXM1 interacts with the promoter of the VEGF gene regulating its activation, which contributes to GBM tumor angiogenesis." (PMID 23404835, 2013). "We inferred that PHGDH is a direct upstream regulator of FOXM1, and targeting PHGDH not only inhibited the aberrant metabolism of tumor cells but also depleted FOXM1 expression, thus attenuating tumor proliferation and invasion." (PMID 23229761, 2013). "The SHH ligand gene and Gli-inducible target genes (FOXM1, IGF2, OSF2, H19, and SPP1) were overexpressed in tumour samples as compared with normal bladder tissue." (PMID 22361633, 2012).
tumor (continued). "The tumor specimens from forty-eight de novo AML patients and forty AML patients in 1st CR and twenty-one healthy controls were analyzed for FoxM1 mRNA expression using qRT-PCR." (PMID 22900969, 2012). "Over expression and knock-down studies of FOXM1 suggested that FOXM1 confers GBM tumorigenicity and increases tumor invasion by enhancing matrix metalloproteinase-2 expression." (PMID 20419098, 2010). "Our study demonstrates that FOXM1 targeting using small molecule inhibitors has the potential to be a novel therapeutic strategy to combat SCLC progression including chemotherapeutic resistance and reshaping the anti-tumor immune response." (PMID 40630538, 2025). "Unlike NB compounds, RCM-1 reduces tumor growth by disrupting the interaction between FOXM1 and β-catenin." (PMID 40612352, 2025). "In summary, our study shows that FOXM1 is a potential therapeutic target in SCLC and its inhibition using small molecule inhibitors (FDI-6 or NB-73) elicits effective antitumor response in multiple SCLC cell lines, xenograft, and spontaneous tumor models." (PMID 40630538, 2025). "Immunohistochemical staining revealed that the expression of FOXM1, Ki67, and MMP9 in the tumor tissues of mice inoculated with Huh7 cells co-cultured with exosomes from hypoxia-induced HepG2 cells significantly increased (p = 0.005, p < 0.001, p = 0.003) when compared to that in the control group." (PMID 40486884, 2025). "Additionally, we found that expression of FOXM1 and HMGA1 was noticeably increased in a tumor grade-dependent manner compared to other TFs (p-value < 0.001, one-way ANOVA)." (PMID 39594773, 2024). "Collectively, our findings suggest that the inhibition of FOXM1 Y575 phosphorylation leads to significant suppression of tumor growth, suggesting that ABL1 kinase inhibitors could be potential clinical agents for FOXM1-overexpressing tumor therapy." (PMID 39060421, 2024). "Furthermore, recent in vitro studies have shown that several tumor suppressor microRNA molecules (i.e., miR34a, miR-802, and miR-877-5p) have binding sites at 3′-UTR of mRNA FOXM1 and inhibit its expression and translation in in vitro and in vivo studies." (PMID 39594778, 2024). "Compounds that inhibit FOXM1 have been shown to suppress TNBC progression and tumor metastasis." (PMID 39834541, 2024). "Moreover, the animal experiments further confirmed that KIAA1429 silencing diminished levels of YTHDF1, FOXM1, HK2, ENO1, and LDHA and suppressed tumor growth." (PMID 39060874, 2024). "Notably, carfilzomib has demonstrated effectiveness in inhibiting FOXM1 expression in AFP‐positive HCC cells, leading to the inhibition of tumour growth." (PMID 38063438, 2024). "Knocking down ALKBH5 inhibited FOXM1 expression in GSCs, and restoring FOXM1 could counteract the consequences of inhibiting ALKBH5 on cell proliferation and tumor formation." (PMID 38398118, 2024). "FOXM1 controls RB1 in two opposing ways, either to turn off the canonical cell cycle inhibitory function of RB1 to enhance cell proliferation or to engage RB1 within repressive transcriptional complexes, which ultimately promote tumor metastasis." (PMID 37686402, 2023). "It has also been shown that treatment of tumour cells with calcitriol or its analogue, EB1089 (EB), reduces the level of the nuclear protein Fork headbox M1 (FOXM1), an oncogene regulating the cell cycle and carcinogenesis, and inhibits tumour proliferation and metastasis." (PMID 37299554, 2023). "Beyond these correlative observations, however, the effect of FOXM1 on PNF transformation or MPNST tumor progression has not been evaluated." (PMID 37686402, 2023).
tumor (continued). "It is speculated that the high expression of FOXM1 will affect the proliferation of MKI67+ progenitor cells and tumor cells, resulting in a worse prognosis." (PMID 37686305, 2023). "Our analysis revealed a pronounced upregulation of FOXM1 mRNA in tumor samples compared to their non-tumorous counterparts (P< 0.001)." (PMID 37817774, 2023). "In addition, FOXM1 is an upstream regulator of various DNA damage repair genes such as XRCC1, BRCA2, RAD51, BRIP1 and NBS1, thereby enabling the tumor cells to resist the action of the genotoxic agents." (PMID 37025658, 2023). "Tumors collected at the end of the experiments showed that M1-21 significantly decreased the size and weight of engrafted tumors compared to controls, correlated with the decreased levels of FOXM1 and FOXM1-regulated CDC25B and PLK1 in M1-21-treated tumor samples." (PMID 37344857, 2023). "Indeed, recent studies in ER-positive breast cancer models demonstrated that low doses of novel FOXM1 inhibitors acted synergistically with low doses of CDK4/6 inhibitors (abemaciclib, palbociclib, or ribociclib) to efficiently suppress tumor cell growth." (PMID 37686402, 2023). "Both the FOXM1 inhibitor NB-55 and the SFKi eCF506 also significantly impaired the growth of a second PDX model established from a luminal B–like tumor, suppressed the expression of FOXM1 and its targets, including SRC, and significantly reduced lung metastasis in this model." (PMID 36795481, 2023). "Furthermore, treatment of sgIF loaded HLC9-EVs plus sorafenib effectively reduced the tumor size and the expression of IQGAP1 and FOXM1 in Huh7 xenografts." (PMID 37202772, 2023). "Additionally, FOXM1 overexpression promotes EMT, invasion/metastasis, and tumor-supportive angiogenic outgrowth." (PMID 37174744, 2023). "FOXM1 and its regulatory network have been demonstrated to be the major predictor of adverse outcomes in 39 human malignancies, whereas most FOXO factors are regulators of cellular homeostasis and putative tumor suppressors." (PMID 37401400, 2023). "Experiments showed that the downregulation of FOXM1 reduced the expression and function of the matrix metalloproteinase-2/9 (MMP-2/9) and vascular endothelial growth factor (VEGF), leading to the inhibition of tumor invasion, migration, and angiogenesis." (PMID 35646056, 2022). "Furthermore, IHC staining of tissue sections showed that the tumour tissues from the SH3PXD2A-AS1 knockdown group had a weaker staining intensity of Ki67 and FOXM1 than those from the control group." (PMID 35410446, 2022). "FOXM1 protein expression in BRCA, CESC, LUAD, STAD and THCA tumor tissues was significantly higher." (PMID 36435510, 2022). "Administration of nattokinase was shown to inhibit the expression of transcription factors CD31, FOXM1, CD44, and vimentin that regulate tumor proliferation, survival, and drug resistance in a mouse model of liver cancer, thereby reducing the tumor growth rate." (PMID 35883536, 2022). "Moreover, the LNEs showed increased inhibition of tumor growth of M subtype TNBC via restoration of CDH1/E-cadherin, and suppression of forkhead box M1 (FOXM1) expression." (PMID 35631368, 2022). "The FOXM1 inhibitor significantly lowers PD‐L1 levels and tumor growth in vitro and in vivo without any side effects on vital normal tissues." (PMID 35975458, 2022). "It was predicted that the genes such as FOXM1 and MYBL2 were activated while HNF4A and PPARGC1A were inhibited in tumor cells, which drove liver tumor, digestive organ tumor, abdominal neoplasm, tumorigenesis of tissue, neoplasia of cells and oxidation of lipid." (PMID 36212481, 2022). "Tumor cells at the outer part of the “pseudo-papillary” structure were CA9-positive (CA9+)/HIF-1α+, whereas cells at the inner part of this structure were CA9−/HIF-1α+ and nestin+/FOXM1+." (PMID 35785200, 2022). "High-throughput sequencing discovered that FOXM1 expression incremented in tumor tissues comparing to matched non-tumorous tissues." (PMID 35842667, 2022).